ANXA2P2 (annexin A2 pseudogene 2)
Description:
Calcium-regulated membrane-binding protein whose affinity for calcium is greatly enhanced by anionic phospholipids. It binds two calcium ions with high affinity. May be involved in heat-stress response.
Synonyms: formerly ANX2P2; ANX2L2; LPC2B
Gene: Processed pseudogene on chromosome 9 (33,624,274 to 33,625,293, forward strand). Ensembl gene ENSG00000231991.
Subcellular location: Secreted, extracellular space, extracellular matrix, basement membrane; Melanosome
Diseases named in the same sentence as ANXA2P2 in open-access papers:
ANXA2P2 is named in the same sentence as 15 diseases in open-access papers, as found by Europe PMC text mining. Sharing a sentence is not in itself a finding about the gene and the disease. The quoted sentences say what the papers report.
glioma (12 papers, 2017 to 2025). A benign or malignant brain and spinal cord tumor that arises from glial cells (astrocytes, oligodendrocytes, ependymal cells). "ANXA2P2 has been reported as an oncogenic lncRNA, with higher expression in glioma and association with glioma progression or poorer prognosis." (PMID 35083143, 2021). "Moreover, higher ANXA2P2 expression could be potentially associated with glioma progression or poorer prognosis." (PMID 35083143, 2021). "Moreover, high expression level of ANXA2P2 is associated with adverse outcome of glioma patients." (PMID 31681595, 2019). "The expression of lncRNA Annexin A2 Pseudogene 2 (ANXA2P2) is markedly upregulated in glioma tissues and cells." (PMID 39272133, 2024). "ANXA2P2 is up-regulated in glioma cells, and it modulates the aerobic glycolysis and proliferation of glioma cells through ANXA2P2/miR-9/LDHA axis." (PMID 34819492, 2021). "In our study, we screened out five pseudogenes (ANXA2P2, EEF1A1P9, FER1L4, HILS1, and RAET1K) that were differentially expressed between LGG and GBM and were associated with the prognosis of glioma patients." (PMID 31681595, 2019). "EEF1A1P9 was a protective factor (HR < 1), and ANXA2P2, FER1L4, HILS1, and RAET1K were defined as risk factors (HR > 1) in glioma." (PMID 31681595, 2019). "The annexin A2 pseudogenes (ANXA2P1, ANXA2P2, and ANXA2P3) are significantly upregulated in glioma and are associated with adverse outcome of glioma patients." (PMID 31681595, 2019). "Our findings are consistent with this and indicate ANXA2P2 can be a candidate therapeutic target for glioma." (PMID 31681595, 2019). "Cox regression analyses suggested that ANXA2, ANXA2P1 and ANXA2P2 were the independent prognosis factors for gliomas." (PMID 29291003, 2017). "Subsequent multivariate analysis results revealed that in addition to increasing age, KPS, grade and histology, high expression of ANXA2, ANXA2P1 and ANXA2P2 (HR: 1.883, P=0.002; HR: 2.444, P<0.001; HR: 2.053, P=0.001) were also the independent prognosis factors for survival of glioma samples." (PMID 29291003, 2017). "Previously, it has been reported that high expression of pseudogene ANXA2P2 in hepatocellular carcinoma could inhibit its invasion and metastasis, yet high ANXA2P2 expression may promote invasive growth and metastasis of glioma cells to surrounding tissues." (PMID 35211410, 2022). "Additionally, down-regulation of ANXA2, ANXA2P1 and ANXA2P2 might contribute to the improvement of the OS for glioma patients who received chemotherapy and radiotherapy." (PMID 29291003, 2017). "Furthermore, Kaplan–Meier curve and Cox regression analyses showed that the high expression of ANXA2 and its pseudogenes were correlated with the poor OS of glioma patients, and the aberrantly expressed ANXA2, ANXA2P1 and ANXA2P2 were the independent prognosis factors for gliomas." (PMID 29291003, 2017). "The T cell depletion-related prognostic model was developed based on seven prognostic genes (HSPB1, HOXD10, HOXA5, SEC61G, H19, ANXA2P2, HOXC10) in glioma." (PMID 36531217, 2022). "Meanwhile, among four glioma subtypes, it was found that ANXA2P1, ANXA2P2, and ANXA2 are preferentially expressed in the mesenchymal subtype and less expressed in the proneural subtype." (PMID 34947885, 2021). "Another five pseudogenes, ANXA2P2, EEF1A1P9, FER1L4, HILS1, and RAET1K, are connected with glioma." (PMID 34947885, 2021). "It was indicated that miR-9 has a negative correlation with the ANXA2P2 mRNA target, and overexpression of this miRNA suppresses the cell proliferation and aerobic glycolysis of glioma cells by binding to LDHA 3′UTR." (PMID 34947885, 2021). "In addition, pseudogenes ANXA2P2, EEF1A1P9, FER1L4, HILS1, and RAET1K were found to be significantly correlated with glioma survival." (PMID 33378744, 2020).
hepatocellular carcinoma (8 papers, 2019 to 2024). A malignant tumor that arises from hepatocytes. "ANXA2P2 is a potential immunological and prognostic signature gene, impacting the pathogenies and prognosis of ovarian serous cystadenocarcinoma and hepatocellular carcinoma, and functioning in the progression of glioblastoma." (PMID 38542485, 2024). "It has also been reported that higher ANXA2P2 expression promotes the aggressive phenotypes of hepatocellular carcinoma." (PMID 35083143, 2021). "ANXA2P2 was up-regulated in hepatocellular carcinoma (HCC) tumor tissues and in HCC cells." (PMID 37415734, 2023). "ANXA2P2 is one of three pseudogenes of annexin A2 that have recently been shown to be aberrantly transcribed in hepatocellular carcinoma (HCC) cells." (PMID 33194647, 2020). "ANXA2P2 (annexin A2 pseudogene 2) is one of three pseudogenes of annexin A2 that have recently been shown to be aberrantly transcribed in hepatocellular carcinoma (HCC) cells." (PMID 30881525, 2019).
glioblastoma (4 papers, 2017 to 2024). The most malignant astrocytic tumor (WHO grade IV). "In a cell experiment, pseudogene ANXA2P2 knockdown showed its tumor suppressor function by inhibiting the PI3K/PKB pathway in glioblastoma cells." (PMID 36531217, 2022). "The results indicated ANXA2, ANXA2P1 and ANXA2P2 may be related to molecular markers of mesenchymal and proneural subtypes of glioblastomas." (PMID 29291003, 2017). "Additionally, knockdown of pseudogene ANXA2P2 could significantly inhibit the progressive invasion and metastasis of glioblastoma cells via the PI3K/PKB pathway." (PMID 35211410, 2022). "Meanwhile, among the four glioblastoma subtypes, ANXA2P1, ANXA2P2 and ANXA2 were found to be preferentially expressed in mesenchymal subtype and less expressed in proneural subtype." (PMID 29291003, 2017). "Among four glioblastoma subtypes, ANXA2P1 and ANXA2P2 were preferentially expressed in mesenchymal subtype and less expressed in proneural subtype." (PMID 29291003, 2017). "In this study, Differentially Expressed Pseudogenes (DEPs) between glioblastomas and non-tumor controls were found by bioinformatics analysis, of which the annexin A2 pseudogenes (ANXA2P1, ANXA2P2 and ANXA2P3) were significantly up-regulated, along with the parent gene annexin A2 (ANXA2)." (PMID 29291003, 2017).
cervical cancer (2 papers, 2021 to 2026). A primary or metastatic malignant neoplasm involving the cervix. "On the other hand, the expression of the lncRNA ANXA2P2 was increased in cisplatin-resistant cervical cancer cells and tissue samples." (PMID 41362671, 2026). "Next, DDP-resistant cervical cancer cells were co-transfected with si-ANXA2P2 and miR-361-3p inhibitor, exposed to 1, 2, 4, 8, 16, or 32 μg/ml DDP, and examined for cell viability." (PMID 35083143, 2021). "In this study, the aberrant upregulation of ANXA2P2 in DDP-resistant cervical cancer cells and tissues was confirmed." (PMID 35083143, 2021). "In DDP-resistant cervical cancer cells, miR-361-3p overexpression was downregulated, whereas miR-361-3p inhibition upregulated ANXA2P2 expression." (PMID 35083143, 2021). "The effects of the ANXA2P2/miR-361-3p axis towards the growth, metastasis, and apoptosis of cervical cancer in vivo were evaluated on the xenograft nude mice model." (PMID 35083143, 2021). "In DDP-resistant cervical cancer cells, ANXA2P2 knockdown upregulated miR-361-3p expression but downregulated SOX9 expression." (PMID 35083143, 2021). "The effects of the SOX9/lncRNA ANXA2P2/miR-361-3p/SOX9 regulatory loop on cervical cancer cell growth and resistance to DDP have been demonstrated." (PMID 35083143, 2021). "The dynamic effects of the lncRNA ANXA2P2/miR-361-3p axis on DDP-resistant cervical cancer cells were examined." (PMID 35083143, 2021). "The correlation of ANXA2P2 expression with the overall survival in patients with cervical cancer was subsequently analyzed using a Cox proportional hazard regression model on the linkedOmics website based on TCGA-CESC data." (PMID 35083143, 2021). "LncRNA ANXA2P2 knockdown inhibited DDP-resistant cervical cancer cell growth and resistance to DDP, whereas the effects of lncRNA ANXA2P2 knockdown were partially reversed by miR-361-3p inhibition." (PMID 35083143, 2021). "LncRNA ANXA2P2 expression was elevated in DDP-resistant cervical cancer cells and tissues." (PMID 35083143, 2021). "Higher ANXA2P2 expression predicted poorer overall survival in patients with cervical cancer." (PMID 35083143, 2021). "After confirming ANXA2P2 targeting and inhibiting miR-361, the dynamic effects of ANXA2P2 and miR-361-3p on DDP-resistant cervical cancer cells were detected." (PMID 35083143, 2021). "Collectively, SOX9, lncRNA ANXA2P2, and miR-361-3p form a regulatory loop, modulating DDP-resistant cervical cancer cell growth and response to DDP treatment." (PMID 35083143, 2021). "SOX9 expression was elevated in DDP-resistant cervical cancer cells and tissues, and SOX9 activated lncRNA ANXA2P2 transcription by binding." (PMID 35083143, 2021). "ANXA2P2 knockdown inhibited DDP-resistant cervical cancer cell growth and resistance to DDP, whereas the effects of ANXA2P2 knockdown were partially reversed by miR-361-3p inhibition." (PMID 35083143, 2021). "The specific functions of the SOX9/lncRNA ANXA2P2/miR-361-3p/SOX9 regulatory loop on the growth and DDP-resistance of cervical cancer cells were demonstrated." (PMID 35083143, 2021). "However, the role of ANXA2P2 in cervical cancer remains unclear." (PMID 35083143, 2021). "SOX9 expression was elevated in DDP-resistant cervical cancer cells and tissues, and SOX9 activated ANXA2P2 transcription by binding." (PMID 35083143, 2021). "Research has revealed a regulatory loop involving the SRY-box transcription factor 9 (SOX9) gene/lncRNA annexin A2 pseudogene 2 (ANXA2P2)/miR-361-3p/SOX9 regulatory axis, which impacts cell growth and resistance to the chemotherapeutic drug cisplatin in cervical cancer." (PMID 41362671, 2026). "Furthermore, SOX9 levels were found to be higher in cervical cancer cells and tissues that were resistant to cisplatin, and SOX9 promoted the transcription of lncRNA ANXA2P2 by binding to it." (PMID 41362671, 2026).
cervical cancer (continued). "ANXA2P2 knockdown inhibited the growth of DDP-resistant cancer cells and elevated the sensitivity of DDP-resistant cervical cancer cells to DDP, which could be partially restored by miR-361-3p inhibition." (PMID 35083143, 2021). "Thus, SOX9, ANXA2P2, and miR-361-3p form a regulatory loop, modulating DDP-resistant cervical cancer cell growth and response to DDP treatment." (PMID 35083143, 2021). "Similar to SOX9, ANXA2P2 expression was dramatically upregulated in DDP-resistant Caski/DDP and HeLa/DDP cells compared with that in original Caski and HeLa cells, and upregulated in DDP-resistant cervical cancer tissues compared to those in non-resistant samples." (PMID 35083143, 2021).
ovarian serous cystadenocarcinoma (2 papers, 2022 to 2024). A malignant serous cystic epithelial neoplasm arising from the ovary. "Although the effect of pseudogene ANXA2P2 on some tumors has been reported in a few literatures, the therapeutic potential and prognostic value of ANXA2P2 in ovarian serous cystadenocarcinoma (OV) have not been elucidated." (PMID 35211410, 2022).
astrocytoma (1 paper, 2017). "GBM presented a significant higher expression of ANXA2, ANXA2P1 and ANXA2P2 than astrocytoma (A, P=0.006, P=0.030 and P=0.005, respectively) and oligodendroglioma (OD, P<0.001, P=0.004 and P<0.001, respectively)." (PMID 29291003, 2017).
ovarian carcinoma (1 paper, 2022). A malignant neoplasm originating from the surface ovarian epithelium. "Meanwhile, univariate and multivariate Cox regression analyses were performed on ANXA2P2 for ovarian cancer, manifesting that the pseudogene ANXA2P2 can be used as an independent prognostic factor without relying on ANXA2." (PMID 35211410, 2022).
prostate carcinoma (1 paper, 2023). A carcinoma that arises from epithelial cells of the prostate gland. "Our scRNA-seq analysis detected greater expression of ANXA3, ANXA2, ANXA2P2, and AHNAK2 in aggressive prostate cancer." (PMID 37476073, 2023).
cancer (7 papers, 2019 to 2024). A tumor composed of atypical neoplastic, often pleomorphic cells that invade other tissues. "Transcriptional expression landscapes of ANXA2P2 in 33 human cancers compared with normal tissues were obtained from TCGA or GTEx datasets." (PMID 35211410, 2022). "KM-plot analysis manifested that high ANXA2P2 expression was relevant to adverse PFI in seven cancers, containing HNSC, LGG, LIHC, MESO, PAAD, OV, USC, and UVM." (PMID 35211410, 2022). "The relationship for ANXA2P2 expression to key regulatory genes was explored using coexpression analysis in pan-carcinoma." (PMID 35211410, 2022). "Thus, in our study, we would comprehensively analyze the relevance between ANXA2P2 expression patterns and prognostic characteristics in pan-carcinoma firstly." (PMID 35211410, 2022). "Also, TIMER2.0 also displayed the landscape of ANXA2P2 correlating with various immune infiltrates in pan-carcinoma via different algorithms in spite of little inconsistency among various algorithms but without too much discrepancy." (PMID 35211410, 2022). "Therefore, ANXA2P2 acts on DDP-resistant cancer cells through targeting miR-361-3p." (PMID 35083143, 2021). "The ANXA2P2 expression levels in cancer tissues and adjacent nontumor tissues in the validation group, consisting of 49 patients, were detected and verified by qRT-PCR." (PMID 30881525, 2019).
tumor (7 papers, 2017 to 2023). "Therefore, we employed GSVA, GSEA, WGCNA, gene mutation, and independent prognostic analysis to explore the impact of ANXA2P2 on the tumor-related pathway, mutation site, and prognosis prediction according to its different expression patterns in OV." (PMID 35211410, 2022). "In addition, ANXA2P2 had significant association with common tumor-related regulatory genes such as TNF-α signaling via NF-κB, TGF-β signaling, DNA repair, hypoxia, autophagy, pyroptosis, and ferroptosis." (PMID 35211410, 2022). "The results showed that the volumes of xenograft formed by Caski/DDP cells with the ANXA2P2 knockdown group were significantly inferior to those formed in the control group, while miR-361-3p knockdown dramatically promoted tumor volumes." (PMID 35083143, 2021). "Next, the relationship for ANXA2P2 expression to tumor purity, stromal score, and immune score was also investigated, indicating that ANXA2P2 was most significantly associated with both immune score and stromal score in DLBC, GBM, LAML, LGG, OV, PCPG, PRAD, and THCA." (PMID 35211410, 2022). "In addition, the correlations between ANXA2P2 and tumor stages were analyzed based on TGCA." (PMID 35211410, 2022). "IHC staining results indicated that the knockdown of ANXA2P2 observably promoted E-cadherin protein expression, while inhibiting N-cadherin and Vimentin expression, while miR-361-3p knockdown exerted opposite effects on the tumor metastasis protein expressions." (PMID 35083143, 2021).
ANXA2P2 also shares sentences with these, for which no sentence is quoted: breast carcinoma (1 paper); liver cancer (1); oligodendroglioma (1); Pan (1); prostate tumor (1).